NF2 (NF2, moesin-ezrin-radixin like (MERLIN) tumor suppressor)
Diseases named in the same sentence as NF2 in open-access papers (continued):
Sharing a sentence is not in itself a finding about the gene and the disease.
meningioma (continued). "The combination of bevacizumab and everolimus for recurrent meningiomas, though not specifically in patients with NF2, resulted in stable disease for the majority of patients and performed similarly to bevacizumab alone." (PMID 34885143, 2021). "OGN is known to interact with p-mTOR and NF2 during meningioma development, but how OGN affects these other proteins is not clear." (PMID 33622177, 2021). "Despite the high frequency of NF2 alterations in the pediatric group, the tumors did not fall into the cluster of NF2-altered adult meningiomas." (PMID 34495383, 2021). "Despite this, the potential involvement of NF2 in the development of sporadic meningioma still remains controversial because it is not a hallmark of these tumors." (PMID 34868937, 2021). "In addition to NF-2, SMARCB1 is now recognized as a driver in meningioma development with a strong predilection for the anterior falx cerebri region." (PMID 34638590, 2021). "One meningioma that featured only minor atypical criteria had the homozygous deletion of CDKN2A/B, in the absence of NF2 mutation." (PMID 33670055, 2021). "It is characterized by multiple peripheral schwannomas without the presence of NF2 stigmata like bilateral vestibular schwannomas, or other intradural NF2 manifestations like meningiomas or ependymomas." (PMID 33804463, 2021). "Genetic alterations of the NF2 gene are found in 60% of sporadic meningiomas regardless of grade, suggesting an initial role in the meningeal tumorigenesis." (PMID 34359639, 2021). "Unlike NF2, TRAF7 mutations were missense (Q384E, N520S, Q539H, G560C, Y563C, S629T, R653Q), most having been described in meningioma, in correlation with SB location." (PMID 31963394, 2020). "Genomic sequencing was also performed and mutations in NF2, TRAF7, SMO, KLF4, and AKT1 did not predict RB1 S780 staining or progression in grade 1.5 meningiomas." (PMID 33346248, 2020). "Half of our non-NF2 meningiomas (NF2-positive by Western blotting) contained no detectable mutations according to our genotyping screening, and further in-depth sequencing analysis is required, which is in agreement with the published literature." (PMID 32070062, 2020). "Comparison of the AKT1 E17K and NF2-negative mRNA expression levels determined that IL-10 mRNA was significantly elevated in the grade I NF2 negative meningioma tissues." (PMID 32070062, 2020). "The age of patients with an additional non-VS schwannoma or meningioma, but not meeting strict NF2 criteria, is significantly higher compared to the unilateral VS group." (PMID 33013614, 2020). "SMARCB1 mutations, involved in gene expression regulation and also located in close proximity to NF2 on chromosome 22, have also been identified in particularly atypical meningiomas in prior work, but were not identified in our matched tumor pairs." (PMID 31191822, 2019). "By crossing transgenic mice expressing Cre under the PTGDS promoter to Nf2flox/flox mice, biallelic Nf2 inactivation in meningioma precursor cells was achieved, without the need for exogenous Cre delivery." (PMID 31652973, 2019). "Roughly 20% of meningiomas do not present obvious genetic alteration, while the most common genetic alteration is the inactivation of the NF2 gene coding for the protein Merlin." (PMID 31671850, 2019). "The tumor suppressor gene, neurofibromin 2 (NF2), is well studied in the context of meningioma." (PMID 31191822, 2019). "Homozygous deletion of Nf2 in mice is embryonically lethal, and heterozygous Nf2 knockout mice develop osteosarcomas but not meningiomas." (PMID 31652973, 2019).
meningioma (continued). "Intriguingly, our results showed that STX3451 and STX2895 were not as effective against a permanent NF2 wild type malignant meningioma cell line, IOMM-Lee, indicating that NF2 status could be important for the effects of these compounds." (PMID 31730023, 2019). "Primary VS cells responded more dramatically to mifepristone than arachnoid cells with or without the NF2 gene, suggesting that schwannoma cells are more responsive than meningioma cells to this drug." (PMID 29615643, 2018). "Recent studies utilizing high throughput whole-exome and whole-genome sequencing have identified two distinct subtypes of sporadic meningiomas: tumors with or without an inactivated NF2 gene." (PMID 28193203, 2017). "In their meningioma panel they did not detect recurrent deletions of the regions of synteny with the human NF2 gene." (PMID 29073243, 2017). "Even in the 309 meningiomas with chromosome 22 loss, these canonical non-NF2 mutations were mutually exclusive with NF2 mutations (p = 0.02), suggesting that loss of chromosome 22 may not be driving bi-allelic inactivation of NF2 in tumors with non-NF2 driver alterations." (PMID 28713588, 2017). "Treatment of NF2-expressing meningioma cells with Mek or Akt inhibitors did not inhibit tumor cell proliferation in vitro (IC50 > 20 μM)." (PMID 25596744, 2015). "Using CRISPR-Cas9 genome editing, we generated isogenic human arachnoidal cell lines (ACs), the origin cell type for meningiomas, expressing or lacking NF2." (PMID 26219339, 2015). "Interestingly, we observe increased SGK1 transcription and protein expression in NF2-CRISPR ACs and in primary NF2-negative meningioma lines." (PMID 26219339, 2015). "Intriguingly, NF2 (neurofibromatosis-2; a gene known to be frequently involved in development of meningiomas) promoter methylation does not play a key role in meningioma development." (PMID 26101774, 2015). "Van Tilborg and co-workers reported hypermethylation of p16 in 62% of meningiomas with LOH of NF2 (located on 22q12.2) in contrast to the normal karyotype." (PMID 24722350, 2014). "Unlike patients with sporadic tumors, NF2 patients often have multiple meningiomas, vestibular schwannomas, and ependymomas." (PMID 23555840, 2013). "NF2-related meningiomas were not effectively treated by bevacizumab in this analysis of NF2 patients treated for their progressive vestibular schwannomas." (PMID 23555840, 2013). "NF2, in contrast to neurofibromatosis type 1 (NF1) is characterised by the development of schwannomas, meningiomas and ependymomas, with the great majority of patients developing bilateral schwannoma involvement of the superior vestibular branch of the eighth cranial nerve." (PMID 19545378, 2009). "Analysis of 40 CpG sites distributed within 750 bp of the promoter region suggests that NF2 promoter methylation does not play a major role in meningioma development." (PMID 17222329, 2007). "Genetic alterations of the Nf2 gene are present in 60% of sporadic meningiomas regardless of grade, suggesting their initiating role in meningeal tumorigenesis; meanwhile, CDKN2A (p16INK4a), p14ARF, and CDKN2B (p15INK4b) are thought to be responsible for progression to higher grades of meningioma." (PMID 39996452, 2025). "The Phase II (NCT03071874) study investigating the use of vistusertib, the oral dual mTORC1/mTORC2 inhibitor in NF2-related schwannomatosis patients with either progressive or symptomatic meningiomas failed to meet the primary endpoint of a 20% volume decrease." (PMID 40149634, 2025). "No NF2 alterations were found in our pediatric cases, and we could not assess SMARCE1 mutations in the clear-cell meningioma due to limited NGS panel coverage." (PMID 40951339, 2025).
meningioma (continued). "Unlike previous reviews that primarily catalog FAK biology and inhibitor development, this work provides a direct mechanistic comparison between GBM and NF2-mutant meningioma to illustrate how genetic context - not histological grade or target abundance - dictates therapeutic relevance." (PMID 41487565, 2025). "Unlike GBM, NF2-mutant meningiomas offer a biologically grounded rationale for FAK inhibition." (PMID 41487565, 2025). "However, it is important to note that the drug repurposing in this study was conducted on sporadic VS and meningioma without available information on potential NF2 gene alterations—a key limitation when assessing its specificity to NF2-SWN." (PMID 41437121, 2025). "NF2 mutation severity score, loss of chromosome 1p, deletion of CDKN2A/B, and global methylation status have been identified as negative prognostic factors for meningioma." (PMID 40562609, 2025). "The main limitation of the public GEO datasets is that we could not determine which of the recurrent meningiomas were 1p-22q-NF2-." (PMID 39726707, 2024). "Furthermore, we did not compare NF2-patients' meningiomas with other subtypes of sporadic meningiomas." (PMID 37752594, 2023). "Meningiomas in the first group have the best prognosis, are distinguished by the lack of NF2 alterations and chromosomal instability, and may be responsive to cytotoxic drugs." (PMID 37296907, 2023). "Furthermore, several typical meningioma locations have distinct related genomic markers (e.g., anterior skull base: SMO, AKT1E17K, TRAF7; central skull base: AKT1, KLF4, TRAF7, POLR2A, Convexity: NF-2, LOH chromosome 22, BAP1)." (PMID 38017560, 2023). "Only 4 cases presented with no macrophage infiltration in sporadic NF2-altered meningiomas." (PMID 37752594, 2023). "In a follow-up study, the same authors reported that meningothelial proliferation and meningioma frequency increased, without variations in the tumor grade, in mice nullizygous for the tumor suppressor p16 (Ink4a), revealing a synergy between NF2 and p16 inactivation in meningioma development." (PMID 38001599, 2023). "The present case demonstrates that NF2/SMARCB1-mutant meningiomas are not exclusive to midline sagittal localization but may be also intra-ventricular." (PMID 35049691, 2022). "We found that the prognosis of the meningiomas was not different location-wise (5-year PFS: 82.1% in “Supratentorial” vs 86.7% in “Infratentorial”, p = 0.18) but was different mutation-wise (5-year PFS: 77.9% in NF2 vs. 90.3% in non-NF2, p = 0.04." (PMID 35570314, 2022). "Moreover, a national Alliance-sponsored cooperative group phase II clinical trial evaluated the efficacy of SMO, AKT1, and FAK inhibitors for recurrent or progressive meningiomas with targetable alterations in SMO, AKT1, and NF2, respectively (NCT02523014/A071401)." (PMID 35712491, 2022). "From a molecular perspective, meningiomas are divided between NF2 mutant and non-mutant meningioma." (PMID 36010600, 2022). "However, most of the infratentorial tumours in which GTR was not achieved were non-NF2 meningiomas (4.7% in “Infratentorial NF2” vs. 26.0% in “Infratentorial non–NF2”, p = 0.04)." (PMID 35570314, 2022). "In meningiomas, the absence of trimethylation of H3K27 (H3K27me3) has been shown to be associated with more aggressive growth of tumor, as well as NF2 and SUFU mutations, allowing us to further stratify grade 1 and 2 tumors according to the 2016 WHO classification system." (PMID 36686824, 2022). "Among meningiomas with GTR, PFS was also different depending on Ki-67 index (Ki-67 ≥ 4 vs. Ki-67 < 4, p = 4.9 × 10–10), FOXM1 protein expression in 111 cases (high vs. low, p = 0.00052), and FOXM1 protein expression in 40 cases of supratentorial NF2 meningioma (high vs. low, p = 0.013)." (PMID 35570314, 2022). "Although we have not found disease-associated variants in NF2 and SMARCB1 genes, it is still possible that undefined variants may contribute to meningioma recurrence." (PMID 35163107, 2022).
meningioma (continued). "There is little evidence that bevacizumab has activity in NF2-related meningiomas." (PMID 34072574, 2021). "A heat map of hierarchical clustering of DBSumNeg for each pairwise compound combination in each cell line showed that meningioma and schwannoma cells each clustered separately by DBSumNeg synergy scores, regardless of NF2 status as seen in the single agent screen." (PMID 34264955, 2021). "Thus, from those 9/10 genes found to be altered in ≥2 grade 1 meningiomas, the NF2 gene was the most frequently carried non-synonymous genetic variants, in combination or not with other synonymous genetic variants, respectively." (PMID 34868937, 2021). "To better understand whether the higher levels of M2 macrophages observed in the NF2-negative grade I meningiomas were activated, we conducted gene expression analysis of four key cytokines shown to be relevant in M2 macrophage polarization." (PMID 32070062, 2020). "NF2 is thought to be involved in meningioma initiation rather than progression." (PMID 32742192, 2020). "Second, for NF2 mutant meningiomas, which also formed 2 different sub-clusters, one of the subgroups revealed a distinct hypermethylated phenotype and was significantly enriched for atypical CNV-high samples (P=0.03 (two NF2 cluster comparison), Fisher’s exact test)." (PMID 28195122, 2017). "Furthermore, we did not detect a significant difference in recurrence rates between high-grade meningiomas with canonical low-grade driver alterations and those without, or between NF2-mutant and NF2-wild-type low-grade meningiomas." (PMID 28713588, 2017). "We analyzed 36 NF2- meningiomas (defined as presenting either an identified NF2 mutation and 22q LOH, or 22q LOH with no NF2 protein expression on Western blot) and 18 NF2+ meningiomas (defined as presenting NF2 protein expression with no 22q LOH and no NF2 mutation)." (PMID 26418719, 2015). "The role of Paks in NF2-related meningioma, however, has not previously been examined." (PMID 25596744, 2015). "NF2 has not been shown to directly regulate the cell cycle; however its presence promotes cell cycle arrest in schwannoma, primary endothelial, mesothelioma, and patient-derived meningioma cells." (PMID 23308224, 2013). "Thus, we conclude that methylation is unlikely to play a major role in silencing of the NF2 gene in meningioma." (PMID 17222329, 2007). "While our analysis identified a BRCA2 (p.E51K) mutation present alongside NF2 gene loss in the same cancer clone across all tumor samples, it is important to acknowledge that the evidence supporting BRCA2 (p.E51K) as a driver mutation in meningioma is not well-established." (PMID 39935847, 2024). "Moreover, TRAF7 meningiomas express >5-fold higher levels of VEGFA compared to NF2 tumors, suggesting that VEGFA together with other DEGs from the RAP1 signaling pathway may be responsible for the secretory phenotype of KLF4 meningiomas." (PMID 36937440, 2023). "Mutations in NF2 in the absence of chromosome 22 LOH are rarely observed in meningiomas, corroborating the two-hit hypothesis for the function of the NF2 gene as a tumor suppressor in spontaneous meningiomas." (PMID 35402234, 2022). "However, the effect of driver gene mutations, especially NF2 alteration, on the prognosis of meningiomas has not been clearly established, except a few reports stating that their prognosis in all WHO grade meningiomas differs depending on the epigenomic/transcriptomic profiles." (PMID 35570314, 2022). "However, a recent study found the NF2 promoter methylation in only one of 49 tumors examined, and only one of 40 examined CpG sites harbors the feature of this tumor, suggesting that NF2 methylation did not play a major role in meningioma development." (PMID 33014773, 2020).
meningioma (continued). "Clues for reconciling the discrepancy between adverse prognosis in chordoid meningioma and lack of adverse prognosis in low-grade meningiomas may come from an in vitro study where the isolation of meningioma cells lines was hampered when the patient tumor lacked NF2 expression." (PMID 31963394, 2020). "Atypical and anaplastic meningioma exhibit a greater number of chromosomal abnormalities than benign meningioma, but the frequency of the NF2 gene mutations is almost the same as in benign meningioma, indicating that NF2 may not be related to the progression of meningioma." (PMID 33042832, 2020). "The positive correlation of PRKACA with NF2 gene expression, which is downregulated in meningioma, may support this view, as well as the negative correlation of PRKACA expression with the four upregulated genes typically found in recurrent meningiomas (CDC2, MLF1IP, CKS2, and PRC1)." (PMID 31671850, 2019). "To date, there are no molecular targets for meningiomas that have achieved a level of ESCAT I. At best, mTOR pathway activation and NF2 alterations have attained an ESCAT II designation." (PMID 40149634, 2025). "As such, despite everolimus being a highly investigated agent in NF2-SWN, VS and meningioma tumours, from these analyses in IPA there was no similarity in potential kinase targets in meningioma and VS for everolimus." (PMID 41437121, 2025). "In contrast to NF2 meningiomas, no obvious oncogenes were present among DEGs upregulated in TRAF7 meningiomas within the “MAPK signaling pathway” set, underscoring the non-aggressive nature of TRAF7 meningiomas." (PMID 36937440, 2023). "These groups were termed MenG A, B, and C. MenG A meningiomas were almost entirely WHO grade 1, had no cytogenetic changes, and were NF2-wildtype." (PMID 36840836, 2023). "However, another study suggested that NF2 might not be involved in meningioma progression." (PMID 35712491, 2022). "In WHO grade I meningiomas with GTR, tumour location (supratentorial or infratentorial), NF2 status (presence or absence) and Ki-67 index (≥ 4 or not) were used as covariates in the multivariate analysis." (PMID 35570314, 2022). "CD163 is a well-established M2 macrophage marker and has previously been shown using immunohistochemistry to be in high abundance in atypical grade II meningiomas but, unlike previous authors, we correlated CD68 and CD163 expression with NF2 status." (PMID 32070062, 2020). "Western blot analyses of the meningioma cell lines corroborated high levels of protein expression of PAK1 and phospho-PAK1 and absence of NF2 in CH157-MN." (PMID 28552950, 2017). "Despite the encouraging results from sunitinib trial in improving hearing and tumor shrinkage in some NF2 patients with progressive vestibular schwannomas, treatment with bevacizumab, a drug specifically targeting VEGFR, did not result in clinically significant response in meningiomas." (PMID 31970090, 2019). "Importantly, when we screened our cohort of 110 primary, non-recurrent meningiomas (n=66 NF2 atypical, n=12 NF2 benign CNV-high, n=4 non-NF2 benign, CNV-high, n=12 NF2 benign CNV-low, n=12 non-NF2 benign CNV-low and n=4 NF2/SMARCB1), we did not identify any TERT promoter mutations." (PMID 28195122, 2017).